CORO2A (coronin 2A)
Synonyms: IR10; WDR2; CLIPINB
Tractability: Antibody: the Human Protein Atlas places it where antibodies can reach. PROTAC: ubiquitination databases record sites on it; its protein half-life has been measured.
Gene: Protein-coding gene on chromosome 9 (98,120,975 to 98,193,206, reverse strand). Ensembl gene ENSG00000106789.
Subcellular location (Human Protein Atlas): Cytosol; Plasma membrane; Basal body; Vesicles
Gene Ontology:
Molecular function: protein binding; actin filament binding
Biological process: actin filament organization; intracellular signal transduction
Cellular component: transcription repressor complex; actin filament; plasma membrane; brush border
Genetic constraint (gnomAD): Loss-of-function variants: 45 observed, 63.98 expected, observed/expected ratio (o/e) 0.7, 90% interval 0.55 to 0.9. The upper end of that interval is the gene's LOEUF score, 0.9, which puts it in group 3 of 6, group 1 being the genes least tolerant of losing a copy. Missense variants: 610 observed, 715.72 expected, observed/expected ratio (o/e) 0.85, 90% interval 0.8 to 0.91. Synonymous variants: 273 observed, 280.56 expected, observed/expected ratio (o/e) 0.97, 90% interval 0.88 to 1.08.
Homologues: Orthologues: chimpanzee CORO2A (99% identical), macaque CORO2A (98% identical), guinea pig CORO2A (88% identical), rat Coro2a (86% identical), mouse Coro2a (85% identical), dog CORO2A (83% identical), rabbit CORO2A (81% identical), pig CORO2A (73% identical), tropical clawed frog coro2a (69% identical), zebrafish coro2aa (64% identical), zebrafish coro2ab (49% identical), Drosophila melanogaster coro (38% identical), and 1 more. Paralogues in human: CORO2B (60% identical), CORO1B (41% identical), CORO1C (40% identical), CORO6 (39% identical), CORO1A (38% identical), CORO7 (29% identical).
Diseases named in the same sentence as CORO2A in open-access papers:
CORO2A is named in the same sentence as 21 diseases in open-access papers, as found by Europe PMC text mining. Sharing a sentence is not in itself a finding about the gene and the disease. The quoted sentences say what the papers report.
breast carcinoma (2 papers, 2020 to 2025). "In contrast, overexpression of CORO2A at the protein level produced an opposite effect on cell migration in these breast cancer cells." (PMID 32695665, 2020). "Our study confirmed that the CORO2A mRNA level is elevated in breast cancer compared with normal breast tissue via analysis of transcriptional sequencing data from more than 1,000 clinical samples of breast cancer in the GEO and TCGA." (PMID 32695665, 2020). "In a previous study, we determined that the CORO2A transcription level was consistently upregulated in multiple breast cancer cohorts from the four Gene Expression Omnibus (GEO) and TCGA databases." (PMID 32695665, 2020). "Dysregulation of these miRNAs is consistent with the phenotype of CORO2A upregulation in breast cancer." (PMID 32695665, 2020). "Significant overexpression of CORO2A was also validated in breast cancer samples (n = 22) collected in our clinic." (PMID 32695665, 2020). "To further explore the targets of CORO2A in breast cancer, we analyzed the transcription factor and miRNA target networks of positively correlated gene sets generated by GSEA." (PMID 32695665, 2020). "The level of CORO2A transcript was significantly upregulated in breast cancer tissue compared with normal tissue in subgroup analyses based on age, ethnicity, tumor stage, nodal metastatic status, disease subclass, and menopause status." (PMID 32695665, 2020). "The knockdown of CORO2A at the mRNA and protein levels produced a decrease in migration ability in both breast cancer cell lines." (PMID 32695665, 2020). "We used databases from the Cancer Genome Atlas (TCGA) and Gene Expression Omnibus (GEO), and analyzed CORO2A expression and gene regulation networks in breast cancer." (PMID 32695665, 2020). "The knockdown of CORO2A produced a decrease in viability and colony formation in both breast cancer cell lines." (PMID 32695665, 2020). "Loss-of-function experiments further indicated that knockdown of CORO2A reduces cell migration, cell viability, and colony-formation and induces cell cycle arrest in the G0/G1 phase of breast cancer cells." (PMID 32695665, 2020). "CORO2A (coronin 2A) plays a critical role in cell migration and proliferation in breast cancer." (PMID 40362181, 2025). "In addition, we also demonstrated in vitro that knockdown of CORO2A reduces cell migration and proliferation and induces cell cycle arrest in the G0/G1 phase in breast cancer cells." (PMID 32695665, 2020). "Further bioinformatics analysis of public sequencing data and our own RNA-Seq data revealed that CORO2A is probably involved in the epithelial-to-mesenchymal transition process and might have a significant effect on the cell migration of breast cancer." (PMID 32695665, 2020). "In addition, we also studied CORO2A expression in data from patients with breast cancer in The Cancer Genome Atlas (TCGA) and various public databases." (PMID 32695665, 2020). "Moreover, in the current study, further subgroup analysis of multiple clinicopathological features of breast cancer samples in TCGA consistently showed elevated level of CORO2A transcript." (PMID 32695665, 2020). "Moreover, breast cancer patients with elevated expression of CORO2A had a poorer overall survival (OS) and relapse-free survival (RFS) in TNBC." (PMID 32695665, 2020). "Therefore, our analyses suggest that MYC is an important target of CORO2A and that CORO2A acts through this factor to regulate the cell migration, cell cycle, and proliferation capacity of breast cancer." (PMID 32695665, 2020). "Targeting CORO2A may provide promising therapy strategies for breast cancer treatment." (PMID 32695665, 2020). "Moreover, CORO2A promotes the migration and proliferation of breast cancer cells and may have an important function in breast cancer progression." (PMID 32695665, 2020).
breast carcinoma (continued). "And we assessed the expression and subcellular localization of CORO2A in breast cancer cells and found that the CORO2A had a relative higher expression in TNBC than in luminal breast cancer cell lines." (PMID 32695665, 2020). "However, the overexpression of CORO2A did not produce a significantly increased effect on cell viability in MDA-MB-231 and BT549 breast cancer cells (these data were not showed)." (PMID 32695665, 2020).
colon carcinoma (2 papers, 2015 to 2020). "We show that increased expression of coronin 2A is associated with the malignant phenotype of human colon carcinoma." (PMID 26373535, 2015). "Here, we show that expression of coronin 2A is up-regulated in human colon carcinoma." (PMID 26373535, 2015).
colorectal cancer (2 papers, 2021 to 2025). A primary or metastatic malignant neoplasm that affects the colon or rectum. "A previous study showed elevated expression of CORO2A in colorectal carcinoma tissues, and a link between its expression and oncogenic MAPK14 and PRMT5 signaling pathways." (PMID 34884487, 2021). "While some studies have reported its upregulation in breast and colorectal cancers, suggesting a potential oncogenic function, others have reported its downregulation in glioma, where it acts as a tumor suppressor by targeting oncogenes such as CORO2A, APC2, WNT7A, and BOC." (PMID 40431607, 2025).
adenoma (1 paper, 2015). A neoplasm arising from the epithelium. "Histopathological investigation revealed that the expression of coronin 2A in colon tumour cells is up-regulated during the adenoma-adenocarcinoma progression." (PMID 26373535, 2015).
colorectal adenoma (1 paper, 2015). An adenoma that arises from the colon or rectum. "This is the first time it has been reported that increased expression of coronin 2A/CRN5 is associated with the colorectal adenoma-adenocarcinoma progression." (PMID 26373535, 2015).
oral cancer (1 paper, 2021). "In this study, we investigated the molecular mechanisms underlying the aberrant expression of CORO2A in oral cancer, focusing on miRNAs." (PMID 34884487, 2021).
oral squamous cell carcinoma (1 paper, 2021). "The Cancer Genome Atlas (TCGA) analysis revealed that CORO1C, CORO2A, and CORO7 were significantly upregulated in oral squamous cell carcinoma (OSCC) tissues (p < 0.05)." (PMID 34884487, 2021).
pancreatic cancer (1 paper, 2025). "Among the nineteen UDEGs, other than the seven UDEGs reported to be carcinogenic and prometastatic genes involved in pancreatic cancer, the other UDEGs, such as ESM1, PCDH7, CORO2A, CEACAM5, GALNT5 and TMPRSS4, are also involved in other cancers." (PMID 40362181, 2025).
pancreatic ductal adenocarcinoma (1 paper, 2023). An infiltrating adenocarcinoma that arises from the epithelial cells of the pancreas. "Analysis of large cohort data from The Cancer Genome Atlas revealed that expression of CORO1A, CORO1B, CORO1C, CORO2A, and CORO7 was significantly upregulated in pancreatic ductal adenocarcinoma (PDAC) tissues (p < 0.05)." (PMID 37239355, 2023).
rectal cancer (1 paper, 2017). A primary or metastatic malignant neoplasm that affects the rectum. "Genome-wide genotyping in 43 rectal cancer patients using SNP array resulted in identification of nine SNPs as nCRT-responsive SNPs and association of coronin 2A (CORO2A) rs1985859 with nCRT response was validated in 113 rectal cancer patients." (PMID 28272347, 2017).
triple-negative breast carcinoma (1 paper, 2021). An invasive breast carcinoma which is negative for expression of estrogen receptor (ER), progesterone receptor (PR), and human epidermal growth factor receptor 2 (HER2). "A recent study showed that expression of CORO2A was associated with overall survival and relapse-free survival in patients with triple-negative breast cancer; moreover, knockdown of CORO2A reduced malignant transformation and induced cell cycle arrest." (PMID 34884487, 2021).
tumor (6 papers, 2015 to 2025). "CORO2A is specifically related to several tumor-associated miRNAs (such as miRNA-493) and transcription factors (such as MYC)." (PMID 32695665, 2020). "Our present study showed that these miRNAs have tumor-suppressive roles, and miR-125b-5p and miR-140-5p directly regulate the expression of CORO2A in OSCC cells." (PMID 34884487, 2021). "The overexpression of CORO2A increased tumor cell migration." (PMID 36766797, 2023). "Tumor-suppressive miR-125-5p and miR-140-5p directly regulate CORO2A expression in OSCC cells." (PMID 34884487, 2021). "Moreover, we linked coronin 2A to MAPK14 and PRMT5 signalling pathways involved in tumour progression." (PMID 26373535, 2015). "In summary, we found that aberrant expression of CORO2A facilitates the malignant transformation of OSCC cells, and that downregulation of tumor-suppressive miRNAs is involved in CORO2A overexpression." (PMID 34884487, 2021). "Moreover, coronin 2A interacted with PRMT5 (protein arginine N-methyltransferase 5), which modulates the sensitivity of tumour cells to TRAIL-induced cell death." (PMID 26373535, 2015).
cancer (5 papers, 2016 to 2025). A tumor composed of atypical neoplastic, often pleomorphic cells that invade other tissues. "As a result of the in silico analysis, two genes (CORO1C and CORO2A) were selected as candidate cancer-promoting genes that affect the prognosis of PDAC patients." (PMID 37239355, 2023). "The knockdown assays suggested that the expression of CORO2A facilitates cancer cell malignant transformation, e.g., cell proliferation, migration, and invasion." (PMID 34884487, 2021). "Our molecular mechanism study revealed that USP19 has a role as a co-repressor in the transcriptional repression of RAR via the stabilization of CORO2A by its DUB activity, and suggests the possibility that USP19 may be a potent target for anti-cancer and metabolic diseases." (PMID 27129179, 2016). "As expected, CORO2A was detected by immunoprecipitation using an anti-USP19 antibody, and reciprocal immunoprecipitation with an anti-CORO2A antibody also brought down USP19 in non-cancer cells (293T and 3T3-L1 cells) and cancer cells (MCF7 cells)." (PMID 27129179, 2016).
CORO2A also shares sentences with these, for which no sentence is quoted: adenocarcinoma (1 paper); colon tumour (1); glioma (1); heart hypertrophy (1); metabolic disease (1); neuroblastoma (1); preeclampsia (1); Stroke (1).